TMPRSS2 (transmembrane serine protease 2)
Diseases named in the same sentence as TMPRSS2 in open-access papers (continued):
Sharing a sentence is not in itself a finding about the gene and the disease.
infection (continued). "Given the very low expression of TMPRSS2 in neonatal mice and humans, this may explain why neonates are relatively protected against infection with SARS-CoV-2." (PMID 36405732, 2022). "In contrast to SARS-CoV and other group 2B coronaviruses, SARS-CoV-2 has a furin cleavage site between the S1 and S2 subunits, which promotes infection of cells expressing the transmembrane serine protease 2 (TMPRSS2) on their surface, e.g., human respiratory tract epithelial cells." (PMID 35044832, 2022). "Muscle damage could be due to an increase of inflammatory cytokines, explained by the infection of SARS-CoV-2 which targets cells using different receptors such as the TMPRSS2 (type 2 transmembrane serine protease receptors)." (PMID 35682003, 2022). "Furthermore, we show that the infection is spike-ACE2/TMPRSS2-independent through using ACE2 knockdown or receptor blocking experiments." (PMID 35277473, 2022). "SARS-CoV-2 utilizes the S protein to bind to the main receptor ACE2 on the host-cell surface and enters the host cell through membrane fusion with the help of furin and type II transmembrane serine protease (TMPRSS2) or cathepsin L,12 which is a crucial process of infection." (PMID 35484110, 2022). "TMPRSS2 is highly expressed with broader tissue distribution, suggesting that ACE2 expression may be limiting in cellular susceptibility to infection." (PMID 39086962, 2022). "Indeed we observed a much greater increase in infection for Delta (34x) under T2 overexpression conditions and a smaller increase (6x) for Omicron in the presence of overexpressed TMPRSS2." (PMID 35075452, 2022). "Although ACE2 and TMPRSS2 are the best-characterized CoV entry proteins, other cellular factors might be involved in virus entry and infection as well." (PMID 36367091, 2022). "Thus, knockout of TMPRSS2 or deletion of the FCS resulted in impaired infection, low viral titers that were shed from infected ferret animal model, and reduced transmission to co-housed animals." (PMID 34805783, 2021). "As far as we currently know, establishing that SARS-CoV-2–related AKI is related to viral invasion needs simultaneous ACE2 (type 2 angiotensin-converting enzyme) and TMPRSS2 (transmembrane protease, serine 2) expressions in the same site, and detection of viral RNA in those tissues during infection." (PMID 33776785, 2021). "This could, in part, help explain the infection of cell types that may lack TMPRSS2, as priming of the S protein for fusion is an essential part of the infection process." (PMID 33557330, 2021). "However, we did not observe any significant differences in the protein levels of ACE2 or TMPRSS2 upon infection in our proteomics data, rather ACE2 was downregulated in SARS-CoV-2 infected Caco2 and Calu-3 cells." (PMID 33898942, 2021). "Brain cells have the angiotensin-converting enzyme 2 (ACE2) receptors, transmembrane serine protease 2 (TMPRSS2), cathepsin L, and furin, all of which have been identified as important for the process of infection with SARS-CoV-2 (see Zhang and colleagues 2020)." (PMID 33115334, 2021). "In keeping with the ACE2/TMPRSS2 cell surface levels, we also detected viral genome in ERP-S3 cells, although at a lower level, indicating that erythroid progenitors in this stage of differentiation are also susceptible to infection." (PMID 33581053, 2021). "However, TMPRSS2 played a more predominant role in virus replication and infection than cathepsin L in primary cells and animal models." (PMID 33420022, 2021). "Based on lentiviral infection of 293T cells expressing a high and constant level of ACE2 together with a range of expression levels of TMPRSS2 and vice versa, SARS2-S-mediated infection required higher levels of cell-surface TMPRSS2 expression than SARS-S to attain maximum levels of cell entry." (PMID 33558493, 2021). "The host protease TMPRSS2 was required for infection of these cells." (PMID 33507952, 2021).
infection (continued). "Thus, the TMPRSS2 protein is considered an important therapeutic target, creating the potential for infection prevention if inhibited at the early stages of the infection." (PMID 33950107, 2021). "After binding to the ACE-2 receptor, the virus’ spike protein is proteolytically cleaved by transmembrane serine protease 2 (TMPRSS2), which facilitates viral entry into the cells, where viral replication takes place leading to progression of the infection and cell-to-cell transmission." (PMID 34220706, 2021). "Similarly, the inhibitory effect of NCOA7 on SARS-CoV-1 Spike pseudotyped vector infection was also suppressed by TMPRSS2 expression." (PMID 34807954, 2021). "It is possible that GR activity, aside from modulating the immune system, may also influence ACE2 and TMPRSS2 expression in lung cells with potential to affect SARS-CoV-2 uptake/infection." (PMID 34328182, 2021). "Interestingly, deletion of the PRRA is not detrimental to SARS-CoV-2 entry in all cell types in culture, and in TMPRSS2-low Vero E6 cells, the furin cleavage site is rapidly lost upon passage, suggesting that it can actively hinder infection." (PMID 33563656, 2021). "On the other hand, MTX inhibits interactions of DDX39B with S protein and TMPRSS2, indicating that it may act against viral entry during the early stage of infection." (PMID 34709727, 2021). "Finally, 6 days after infection, the viral titer in the culture supernatant of VeroE6 cells was significantly lower than that of VeroE6/TMPRSS2 and HCT-8 cells (P = 0.016 and P = 0.006, respectively)." (PMID 33980675, 2021). "Prostatic hypertrophy, a common problem of the elderly men, may have a role in increased TMPRSS2 expression, which may account for the increased severity of the infection in this age group." (PMID 34336361, 2021). "We found that human bronchial epithelial cells immortalized with hTERT and CDK4 (HBE3-KT) were refractory to infection and expressed undetectable levels of hACE2, but they did express the TMPRSS2 cell surface protease that activates the SARS-CoV-2 spike glycoprotein." (PMID 34724828, 2021). "Finally, recent evidence suggests that an increase in Transmembrane protease serine 2 (TMPRSS2) expression results in increased infection/establishment of infection with lower viral titers." (PMID 33479353, 2021). "We found that DMV formation occurs with infection by SARS-CoV-2 in VeroE6/TMPRSS2 cells (*)." (PMID 33808940, 2021). "Time series transcriptome profiling of Calu-3 cells infected in vitro with a clinical SARS-CoV-2 isolate revealed a strong upregulation of TMPRSS2 mRNA within the very first few hours post infection, whereas at later time points, the levels revert to baseline or even slightly below." (PMID 34198973, 2021). "To test whether PGS also has an inhibitory effect on pSARS-CoV-2 entry, we treated ACE2+ and ACE2/TMPRSS2+ cells with serial threefold dilutions of PGS stock solution containing 15 mg/ml PG root for 1 h before infection with pSARS-CoV-2." (PMID 34035463, 2021). "Camostat, an inhibitor of TMPRSS2, can block the infection of SARS-CoV-2 in human lung cells." (PMID 33441564, 2021). "Thus, the cells on which ACE2 and TMPRSS2 are concurrently present are most prone to the infection of SARS-CoV." (PMID 33437145, 2021). "Additionally, TMPRSS2 & 4 have been identified as contributing to small intestine enterocytes’ productive infection, explaining SARS-CoV-2 RNA being detected in fecal matter." (PMID 33557330, 2021). "Furthermore, zebrafish has an ortholog of TMPRSS2, which encodes an enzyme that activates coronavirus spike protein for binding ACE2 thus allowing infection." (PMID 33757938, 2021). "We next established whether a higher viral titre could overcome the low levels of ACE2 and TMPRSS2 on endothelial cells to mediate productive infection." (PMID 34721846, 2021). "Our data also suggest that SARS-CoV-2 may exploit inflammatory driven upregulation of ACE2 and TMPRSS2 to enhance infection in the ocular surface." (PMID 32502616, 2021).
infection (continued). "Given the increasing uncertainty around the use of vero cells as a reliable model of aspects of SARS-CoV-2 entry, we completed our own analyses with an alternative pseudotyping (lentivirus) system and, importantly, using human cells expressing TMPRSS2 as targets for infection." (PMID 33753152, 2021). "TMPRSS2 plays a dual role in the infection process: it proteolytically cleaves both the S protein, to trigger fusion of viral envelope with the host cell membrane, and the ACE2 tail, to increase the virion uptake, also through the cathepsin L -dependent pathway." (PMID 34201505, 2021). "The interaction between CD9 and TMPRSS2 favors the entry and infection of MERS in murine lungs." (PMID 34394121, 2021). "We find ACE2, TMPRSS2 and AR expression to overlap with the infection sites." (PMID 35602214, 2021). "Angiotensin-converting enzyme 2 (ACE2) is the receptor for the spike protein and is responsible for the initiation of infection, although other host factors, such as TMPRSS-2 and neuropilin-1, may facilitate the viral entry process." (PMID 34634931, 2021). "Additionally, to measure the potential effectiveness of SB treatment on infection inhibition, cellular models based on the Calu3 and VeroE6 cells and their TMPRSS2- expressing derivatives were assessed by viral pseudoparticles (Vpp) infection assays." (PMID 34063247, 2021). "The SFN down-regulates TMPRSS2 levels and results in the protection against infection." (PMID 34527703, 2021). "In summary, current structural and functional information suggests that several related, transmembrane trypsin-like serine proteinases decisively contribute to prime SARS-CoV-2 S protein either in synergy with or in place of TMPRSS2 and therefore promote infection of ACE2-coexpressing cells in vivo." (PMID 33268377, 2021). "Furthermore, SB extracts effectively inhibited SARS-CoV-2 Vpp infection through a TMPRSS2-dependent mechanism." (PMID 34063247, 2021). "Together our data indicate that the human ocular surface epithelium provides an additional entry portal for SARS-CoV-2, which may exploit inflammatory driven upregulation of ACE2 and TMPRSS2 entry factors to enhance infection." (PMID 32502616, 2021). "Infection is also dependent on S protein priming by transmembrane serine protease 2 (TMPRSS2)." (PMID 34690821, 2021). "We speculate that this is because the protease activity of TMPRSS2 might promote infection via direct fusion with the plasma membrane." (PMID 33630831, 2021). "TMPRSS2 expression enhanced infection by SARS-CoV-2 Spike pseudotypes by ~10-fold." (PMID 34807954, 2021). "The sera from the high dose TMPRSS2-deficient mice protected from A/Narita/1/2009 infection but not from A/PR/8/1934 infection." (PMID 34145279, 2021). "Finally, the titer in the culture supernatant 6 days after infection was almost the same for VeroE6/TMPRSS2 and HCT-8 cells (P = 0.678)." (PMID 33980675, 2021). "Transmembrane protease serine 2 (TMPRSS2) is a serine protease up‐regulated by androgen hormones; it is involved in the infection process of many viruses, including coronaviruses, acting on the spike proteins and on ACE2, facilitating virus‐cell membrane fusion." (PMID 32970391, 2020). "For the distributions chosen, our model predicted that the total population of cells infected increased with TMPRSS2 expression, going from ~1640 cells/ml at low to ~5050 cells/ml infected at high mean TMPRSS2 expression level (out of 105 initial target cells/ml) at 1 d post-infection." (PMID 33290397, 2020). "Our results substantiate the hypothesis of an ENS-transmitted nervous system entry in that enteric neurons do express ACE2 and TMPRSS2, thereby meeting the histological prerequisites for such an infection." (PMID 33122999, 2020).
infection (continued). "While our study lacks protein expression data of ACE2 and TMPRSS2, other functional studies utilizing small intestine enteroids showed evidence of active infection of intestinal epithelial cells by SARS-CoV-2, confirming the possibility of COVID-19 infection in the GI tract." (PMID 32545271, 2020). "Moreover, Vero/MSPL cells developed more significant and severe cytopathy than the Vero/TMPRSS2 cells at 72 h post-infection." (PMID 32471322, 2020). "Therapeutics that prevent TMPRSS2 or CTSL from cleaving the virus could also be a means of preventing infections." (PMID 32883010, 2020). "We speculate that they may have a lower risk for infection, but a higher risk for disease severity, due to a lower ACE2 but a higher TMPRSS2 expression." (PMID 32973879, 2020). "Interestingly, our data showed that the additional possibility of priming the SARS‐CoV‐2 S protein by FURIN would potentially render 25% more cells vulnerable for infection as compared to by exclusively TMPRSS2 S protein priming." (PMID 32246845, 2020). "Tongue coating contains cells that coexpress ACE2 and TMPRSS2 and abundantly expressed TMPRSS2, which could theoretically be an infection-promoting factor." (PMID 32825469, 2020). "In addition, we also respectively investigated the changes before and after TMPRSS2 infection with SARS-COV-2 virus in Vero E6 cells and mouse lungs." (PMID 33193689, 2020). "This suggested that the brain may be less susceptible to infection than other tissues with higher expression of ACE2 and TMPRSS2." (PMID 33362695, 2020). "Human angiotensin-converting enzyme 2 (ACE2) serves as a receptor for the S protein, while type II transmembrane serine protease (TMPRSS2), which is responsible for the cleavage and activation of the S protein, comprises a necessary co-receptor for the completion of the infection process." (PMID 33271762, 2020). "Therefore, the TMPRSS2/ADAM-17 balance would be shifted towards TMPRSS2 activation, thus favoring infection by the virus." (PMID 33519802, 2020). "Therefore SARS-CoV-2 requires co-expression of ACE2 and TMPRSS2 in the same cell type for cell entry and infection." (PMID 33228225, 2020). "TMPRSS2 facilitates infection via two independent mechanisms, cleavage of ACE2, which might promote viral uptake, and cleavage of SARS-S, which activates the S protein for membrane fusion." (PMID 33101356, 2020). "However, after infection of Tmprss2 knockout mice with an H3N2 influenza virus, only a slight increase in survival was observed, and mice still lost body weight." (PMID 26889029, 2016). "After infection with a low dose (101 Focus Forming Units (FFU)) of a mouse-adapted H3N2 virus (A/HK/01/68), body weight loss is less severe and survival is increased in Tmprss2 knock-out compared to wild type mice." (PMID 24348248, 2013). "As expected, Tmprss2-deficient mice were not protected from viral spread and pathology after infection with multi-basic H7N7 influenza A virus." (PMID 24348248, 2013). "Also, after infection with mono-basic H3N2 influenza A virus body weight loss and survival was less severe in Tmprss2 mutant compared to wild type mice." (PMID 24348248, 2013). "TMPRSS2 likely plays a key role in the initial infection and spread of the virus; however the importance of this protease on SARS-CoV infection results from a fine balance between two antagonist effects on infection: shedding of the receptor and fusion activation." (PMID 22816037, 2012). "Also, animal models that lack TMPRSS2 reveal a substantially decreased degree of lung pathology and spread of the virus after infections with SARS-CoV and MERS-CoV, emphasizing the essential function of this protease in viral pathogenesis and the potential benefits of therapies targeting TMPRSS2." (PMID 40297833, 2025).
infection (continued). "Some researchers have proposed that sex differences in the expression of hormone-regulated receptors—such as transmembrane serine protease 2 (TMPRSS2) and angiotensin-converting enzyme 2 (ACE2)—may contribute to differential susceptibility to viral entry and infection." (PMID 40918662, 2025). "Higher levels of TMPRSS2 expression may enhance viral entry and increase the severity of infection." (PMID 40026986, 2025). "To investigate whether SARS-CoV-2 can infect cells of the human CNS, we investigated the expression of the SARS-CoV-2 entry receptors ACE2 and TMPRSS2 in post-mortem human brain tissue, which are required for infection of other cell types including airway epithelium." (PMID 38995681, 2024). "We hypothesise that CMs, which do not express TMPRSS2, are more susceptible to Omicron variants, which do not require this protein for infection, than the earlier Delta variant." (PMID 39095802, 2024). "Therefore, Art might inhibit the infection of SARS-CoV-2 by limiting the expression of ACE-2 receptors or TMPRSS2 in host cells." (PMID 38188145, 2024). "After demonstrating that the isoform 1 of TMPRSS2 not only impacts replication of SARS-CoV-2 but also this of YFV, we raised the hypothesis that changes in viral replication of human individuals after infection might depend on different expression of TMPRSS2 isoforms." (PMID 38185627, 2024). "We therefore analyzed the distribution, abundance, and cellular expression of species-specific ACE2 and TMPRSS2 mRNA within the respiratory tract of various animal species via duplex in situ hybridization and compared these to viral antigen distribution following experimental infection." (PMID 38230954, 2024). "When TMPRSS2+ cells are cultured at a mildly acidic pH of 6.8, viruses enter cells via the plasma membrane and late endosomes, which may occur in nasal cavity during initial clinical infection." (PMID 38167417, 2024). "In addition, TMPRSS2 is a key determinant that impacts coronavirus transmission and virus-induced tissue pathologies in the infected host, suggesting the indispensable role of TMPRSS2 to coronavirus entry and pathogenesis at the primary infection sites." (PMID 39606435, 2024). "TMPRSS2 inhibitors were used to determine if they could reduce infection in Mv1Lu cells." (PMID 38033586, 2023). "Although DCs only express low levels of TMPRSS2 compared to epithelial cells of the respiratory, gastrointestinal, or urogenital tract, the present study shows that a functional knockout of TMPRSS2 leads to an altered cytokine secretion pattern under simulation of infection." (PMID 36830955, 2023). "However, TMPRSS2 increased Delta and Delta S375F infection rates." (PMID 37243215, 2023). "Furthermore, researchers have observed higher levels of TMPRSS2 and ACE2 in the lesional skin of AD patients, potentially explaining their susceptibility to SARS-CoV-2 and the likelihood of experiencing more severe symptoms upon infection." (PMID 38204754, 2023). "Further, infection with the SARS-CoV-2 Beta variant lead to a marked infiltration of lymphocytes, neutrophils and macrophages into the lungs of wt, but not TMPRSS2 KO mice; meanwhile, infection-mediated infiltration, measured for wt and TMPRSS2 KO mice, were within the background range." (PMID 36851486, 2023). "Therefore, testosterone-mediated TMPRSS2 modulation may explain male predominance in these infections." (PMID 37371774, 2023). "Interestingly, TMPRSS2 expression significantly reduced CCoV-HuPn-2018pp infection in 293/APN cells but not Huh7 cells, and the underlying mechanism needs further investigation." (PMID 37676001, 2023). "However, cardiomyocytes lack TMPRSS2, questioning relevant direct cardiomyocyte infection." (PMID 35364700, 2022). "Moreover, we found that ACE2 and TMPRSS2 were commonly enriched in intestinal immunity-related pathways and may involve in the biological processes related to infection and T-cell activation." (PMID 35154056, 2022).